TNF (tumor necrosis factor)
Diseases named in the same sentence as TNF in open-access papers (continued):
Sharing a sentence is not in itself a finding about the gene and the disease.
infection (continued). "While for cells with EGDe infection, the alterations of inflammatory cytokines expression were larger with 42.9% TNF‐α reduction and 233.3% IL‐1β increase by 0.5 μmol/L DPI treatment relative to 0 μmol/L DPI treatment." (PMID 30258592, 2018). "At an early stage of infection (7 dpi), only TNF-α levels were significantly increased in lungs of CD18low compared to WT mice." (PMID 30233576, 2018). "In M. pneumonia challenged mice, serum IL-6, IL-1β, and TNF-α were significantly higher in mice after 1 month infection than their saline controls." (PMID 29849498, 2018). "Addition of isotype control antibody, anti-IL-1β, IL-6, or IL-10 antibodies did not significantly affect the generation of T cells expressing IFN-γ or TNF-α during in vitro infection and T cell priming." (PMID 30233599, 2018). "WT mice also showed increased levels of TNF-α and IL-1β after infection (respectively), inflammatory cell recruitment to the knee joint, and tissue inflammatory cell infiltration demonstrated histologically when compared with ST2−/− mice." (PMID 29867945, 2018). "The analysis of the functional profile of CD4 T cells revealed that ILC1s are dispensable for the induction of IFN-γ and TNF-α in this experimental in vitro infection model." (PMID 29623077, 2018). "In both groups of animals, infection with Colombian strain induced a significant increase in TNF-α (NI WT vs. Inf WT, p = 0.02, t = 2.61 and NI IL-4−/− vs. Inf IL-4−/−, p = 0.002, t = 4.74)." (PMID 30622430, 2018). "Our data agree with this, as neutralization of TNF during primary Lm-gp61 infection resulted in increased bacterial burden 3 days post-challenge." (PMID 29438281, 2018). "Previous studies have demonstrated that TNF-α is a contributing factor in the inflammatory response against infection of intracellular micropathogens such as Plasmodium spp., T. gondii, Leishmania major, and Trypanosoma spp." (PMID 30245924, 2018). "The analysis of cytokines response revealed that TNF-α to TGF-β ratio is low as compared to resolved infection." (PMID 29891859, 2018). "Our data reveal anti-Gr1-, but not anti-Ly6G-treatment significantly reduces the production of TGF-β and TNF-α in the hearts of mice, therefore leading to less collagen deposition and reduced cardiac fibrosis on day 21 after infection." (PMID 29868513, 2018). "In the present study, we assessed monocytes/macrophages activation biomarkers in adult patients with MV infection by evaluating plasma levels of sCD163, sCD14 and TNF-α during both the acute and recovery stages of the infection." (PMID 29795672, 2018). "Analysis of gene expression in whole brain confirmed infection triggered CNS inflammation by showing upregulation of mRNA for IL-1β, TNF, and IFN-γ." (PMID 30538705, 2018). "Consistently, we found that TNF expression levels were higher in the spleen after infection with VSV than in uninfected controls." (PMID 29142134, 2018). "Three out of four donors also exhibited increase in infection induced TNFα release upon differentiation to NAFMs." (PMID 30018616, 2018). "Inflammatory mediators in the acute phase of experimental infection - The inflammatory cytokine TNF performs a pivotal role in T. cruzi infection." (PMID 30365644, 2018). "Weak hepatic expression of CD68 was observed in B6.WT and B6.TNF−/− control groups, which was upregulated at day 42 after infection compared to its B6.WT counterpart." (PMID 29403488, 2018). "Outbred mice also displayed significantly less IL-6, MCP-1, and TNF-α expression throughout infection." (PMID 30533047, 2018). "The incidence of serious adverse events such as infections was significantly higher in the group treated with the anti-TNF-α agent compared to placebo (34% versus 9%, p = 0.04) as well as the 6-month mortality rate (58% versus 23%, respectively, p = 0.017)." (PMID 30060508, 2018). "Prominent shifts in TAB1 and TAB2 proteins to a lower electrophoretic mobility were detected upon infection with H. pylori or stimulation with TNF or IL-1β." (PMID 29581850, 2018).
infection (continued). "The cytokine production levels of TNF-α, IL-1β, and IL-10 in the cell-free culture supernatants were significantly enhanced in response to S. aureus at 24 h after infection." (PMID 29523806, 2018). "Tumor necrosis factor (TNF), another inflammatory mediator during TB, is also expressed at a lower level upon infection with the Δnrp strain." (PMID 30381350, 2018). "Among the generated mutant strains, different characteristics were observed in the bacterial growth rates and product levels of NO, IL-6, and TNF-α in RAW 264.7 cells responding to infections of C3, C24 and C30 strains." (PMID 30064361, 2018). "In the case of exosomes released from M. bovis-infected macrophages, a minimum of 2 days of infection was needed to obtain exosomes effective in inducing TNF-α in naive cells." (PMID 29158431, 2018). "Our study shows that the unadjusted incidence of hospitalizations for infection was 3.6 per 100 patient-years for tofacitinib, compared with 2.2 and 2.5 per 100 patient-years in individuals using TNFi and non-TNF biologics, respectively." (PMID 29566769, 2018). "The protective immunity against the TB pathogen is said to be mediated by cytokines such as IFN-γ, TNF-α, IL-12, IL-6 and IL-18 during the initial stage of infection." (PMID 30583589, 2018). "Levels of TNF-α, IL-10 and IL-2 differed between groups on SD 1 already, i.e. before infection, but these discrepancies are compensated for by the paired analysis (normalization to SD 1) applied here." (PMID 29973271, 2018). "Infection also induced a 3.0-fold increase in TNF-α mRNA expression in intact males compared to that in intact females (P < 0.01)." (PMID 30515051, 2018). "This fact illustrates the paradoxical role of TNF-α, important to contain infection in the primary site of infection, but lethal when released systemically in the inflammatory response induced by Gram-negative bacteria." (PMID 30564201, 2018). "During the acute phase of infection, the recognition of T. cruzi by Toll-like receptors on macrophages triggers production of TNF-α and IL-12, which in turn activates other cells, such as natural killers and lymphocytes, to produce IFN-γ." (PMID 29755471, 2018). "The authors noted that 1α,25(OH)2D treatment prior to or post-infection downregulated IL-6 and IL-8 RNA levels and decreased the levels of infection-induced TNFα, IFNβ, and ISG15." (PMID 30115864, 2018). "Increase of 5–10-fold levels in TNFα production in response to human Babesia WA1 strain later in infection, suggested to be produced by CD8+ T cells, and concomitant decrease in IL-10 levels was occurred together with fatal disease in mice." (PMID 29445365, 2018). "TNF-α is an major inflammatory factor in the early stages of infection and has a chemotactic effect on neutrophils." (PMID 29904013, 2018). "At the acute stage of infection, Th1 polarization in young mice spleen was associated with increased IFN-γ and TNF-α producing T cells and a high Tregs/Th17 ratio." (PMID 30619263, 2018). "The ability of cytokines (TNFα in the case of GC, IL-1α for Ct) to exacerbate immune-driven pathology is common to both infections, as is potentially the role of matrix metalloproteinases (MMPs) in tissue disruption." (PMID 30524442, 2018). "TNF-α is primarily produced by macrophages in response to both acute and chronic conditions (trauma, sepsis, infection, rheumatoid arthritis, inflammatory bowel disease, bronchitis, and glomerulonephritis)." (PMID 29304133, 2018). "In the present study, we have further investigated our previous observation that short-term stimulation of human MDM with pro-inflammatory cytokines (IFN-γ and TNF-α), i.e. M1 polarization, before infection induces a partial restriction of HIV-1 replication." (PMID 30250078, 2018).
infection (continued). "The infection of mice with ECTVRevCRD or ECTVRevSECRET expressing the anti-TNF/LT or anti-chemokine activity of CrmD, respectively, allowed us to address the contribution of TNF/LT vs. chemokines to inflammatory and protective responses in vivo." (PMID 29724993, 2018). "The experimental rats’ serum stimulated a pro-inflammatory response induced by infection of P. gingivalis, while the treatment with IgY decreased the levels of IL-6 and TNF-α and shifted the immune response towards an anti-inflammatory response." (PMID 30374625, 2018). "To analyze the specific role of TNF in the accumulation of Mo-M, we employed TNF-competent mice of the BALB/c strain which are highly susceptible to L. major BNI infection and display progressive visceralization." (PMID 29403488, 2018). "The results demonstrated a rapid upregulation of mRNA expression of IFN-β, as well as TNF-α, in MEFs and BMDMs with peak responses at 4 h after infection." (PMID 30233599, 2018). "IOE is unusual for the ehrlichia because it infects endothelial cells, and it elicits shock-like infection driven by TNFα and type I IFNs." (PMID 30080899, 2018). "Rnase3 is an antimicrobial protein secreted in response to infection, and is critical for neutralizing bacterial lipopolysaccharides (LPS) and inhibiting tumor necrosis factor production in human macrophages." (PMID 29443944, 2018). "Specifically, both the CH and CH60 strains inhibited IL-4 and TNF-α expression during the early stage of infection, and both cytokines were up-regulated after 60 hpi." (PMID 29700351, 2018). "It has been reported that inflammatory cytokines, including TNF-α, IL-4, and IL-13, promote mucin gene expression in intestinal epithelial cells and prevent pathogen infection and colonization." (PMID 29867964, 2018). "IFN-γ provides therapeutic potential while TNF-α has been recognized to mediate protection in visceral model of infection." (PMID 29953494, 2018). "The mitochondrial phosphorylation capacity was decreased by IFNγ and TNFα in combination, both when accompanied by infection (-48%, p<0.001) and under un-infected conditions (-36%, p<0.01)." (PMID 30252907, 2018). "In the presence of THC, natural killer (NK) cells show diminished production of tumor necrosis factor alpha (TNF-α) when challenged with infection." (PMID 30402363, 2018). "Intereukin-6, interleukin 1β, and tumor necrosis factor-α are some of the cytokines that are elevated in LPS-induced macrophage to combat the infection." (PMID 30155492, 2018). "Infection leads to a strong increase of CD11c+iNOS+TNF+ inflammatory DCs (here termed Mo-DC) at the infection site." (PMID 29403488, 2018). "In the present study, we observed lower concentrations of Th1 cytokines (IFN-γ, TNF-α, IL-6) on day 3 post-infection) and lower concentrations of one Th2 cytokine (IL-10) in infections of BCG+ donor PBMCs compared to BCG- donor PBMCs." (PMID 30204787, 2018). "Infection induces significant cytokine mRNA over-expression (15- and 38-fold for TNF-alpha and IL-6 respectively), which was significantly down-regulated by the TSA treatment until basal non-infected cells level." (PMID 29986388, 2018). "While TNF signaling is mainly considered pro-inflammatory, its requirement for the anti-inflammation process involved in the resolution of infection and tissue repair is less explored." (PMID 29973541, 2018). "Reduction of these monocyte subsets was associated with diminished percentage of MDMs and MDCs and increased levels of TNF-α, which remained elevated in the lung 48 days after infection." (PMID 30233576, 2018). "In acute disease, TNF is considered the key innate effector responsible for the rapid control of infection." (PMID 29344006, 2018). "Cytokines, such as TNF-α and IL-1β, regulate the inflammatory responses by playing important roles in host defence, infection, and pathogenesis of the disease." (PMID 30127737, 2018).
infection (continued). "Then, we assessed the percentile of IFN-γ or TNF-α producing CD4 or CD8 T cells by flow cytometry at 4 days after initial infection." (PMID 30233599, 2018). "There is a report that MRP14 induces the secretion of TNFα, IL-1β and IL-6 dependent on TLR4, and it is also reported that these inflammatory cytokines can be associated with the pathology during infection with P. berghei." (PMID 29902248, 2018). "The results showed increased TNF-α and IL-12p40 release in the peripheral blood during the entire infection process in mice infected with either the Δ27735 mutant of the WT strain, as compared to the blank group." (PMID 29598830, 2018). "Macrophages sense B. abortus and induce upregulation of IL-12, IL-1β, TNF-α, and IL-6 genes as early as 30 min after infection." (PMID 29942317, 2018). "Different from the control antagomir, MDMs treated with antagomir-HA-3p displayed a downregulated transcription of TNF-α at 12, 24 and 48 h post-infection." (PMID 29327729, 2018). "The TNF blockage demonstrated how vulnerable these animals can become by this infection, reinforcing the importance of this inflammatory mediator in controlling its replication." (PMID 30365644, 2018). "In our study, we used notably earlier times of infection (2 and 36 h), and exosomes produced under all of these conditions had a significant effect on TNF-α stimulation." (PMID 29158431, 2018). "While the secretion of proinflammatory cytokines IL-6 and TNFα was similar in both infections, the output of regulatory IL-10 was significantly higher in wild type infection, indicating that the M5 protein promotes secretion of IL-10." (PMID 29579113, 2018). "IL-1β, TNF-α, or IL-6 present similar patterns of differential expression with a peak at 30 min post-infection when compared with NI cells." (PMID 29942317, 2018). "Accordingly, in previous studies, the use of TNF-α antagonists in subclinically infected people promoted the reactivation of infection by Leishmania spp." (PMID 30539014, 2018). "Interaction between CCR2 and its CC-chemokine ligand recruits monocytes to sites of infection and these monocytes can participate in the initial inflammatory response by producing tumor necrosis factor (TNF) and chemokines." (PMID 30149800, 2018). "Although TNF is essential to clear infection in the liver, it was also reported to be responsible for the disruption of the splenic microarchitecture, which has severe consequences, among other, on T cell migration." (PMID 29472618, 2018). "Studies to investigate the role of specific cytokines and chemokines in the response to infection have shown that these mediators can be beneficial (e.g., IL-6, TNF-α, IL-1, and CXCR1) (62, –, 65), or they can be detrimental (CCR1)." (PMID 29666281, 2018). "In agreement with El-Deeb and Elmoslemany, proinflammatory cytokines' serum levels (TNF-α and IL-6) were markedly elevated to enhance leukocyte migration into the infection site." (PMID 30050645, 2018). "Several pro-inflammatory innate cytokines produced by epithelial cells, such as IL-8, IL-1β, IL-12 and TNF-α, were elevated in saliva after infection." (PMID 29621276, 2018). "L-GSH treatment resulted in decreased levels of TNF-α, an inflammatory cytokine at 15 days post-infection." (PMID 29494546, 2018). "As expected, infection of BMDMs cells with Hh induced a sustained release of IL-6 and TNFα in the supernatants as compared to unstimulated BMDM." (PMID 29636751, 2018). "In the ileum, there was a progressive increase in the expression of IFN-γ and TNF-α genes in GN-CS group from days 2 to 8 of infection." (PMID 30564201, 2018). "In the footpads of L. major-infected WT BALB/c mice from three independent experiments, CpG-ODN 1668 led to a significant increase of IFN-γ, IL-12p35, TNF, and iNOS mRNA expression at 36 h after infection (i.e., 26 h after the last CpG-ODN 1668 injection)." (PMID 29459858, 2018).
infection (continued). "The production of IL-6 and TNFα is essential in mediating the innate immune response to infection, as well as regulating other important homeostatic processes such as wound healing and sleep." (PMID 30214381, 2018). "In Res-treated groups, higher levels of cytokines in serum, including interferon gama, interleukin 12, tumor necrosis factor-alpha and interferon alpha were observed at 7 days post infection." (PMID 30150559, 2018). "At 48 hours after infection, IL-6 and TNF-α were significantly increased in three groups of mice compared to sham groups." (PMID 30337682, 2018). "At week 6 post-infection, increased levels of TNF-α, IFN-γ, IL-12, IL-23 and IL-17 were found in the liver and spleen supernatants associated with reduced levels of TGF-β only in the spleens." (PMID 30410119, 2018). "Previous studies showed that expression of proinflammatory cytokines like interleukin 1, 6 or tumor necrosis factor during PRRSV infection corresponds to the severity of infection." (PMID 29882085, 2018). "The results displayed that mRNA levels of IL-8, IL-6, and TNF-α increased and reached to the peak at 24 h post infection (hpi)." (PMID 30314467, 2018). "After infection with S. mansoni, IL-4 deficient mice produce higher amounts of IFN-γ and TNF-α, but develop a severe and fatal disease." (PMID 30233576, 2018). "IFN-γ is a key effector molecule that synergizes with TNF-α in activating infected APCs, allowing the cells to better control intracellular infection." (PMID 30063728, 2018). "While TNF-α and IL-6 production increased in sole microglia post-infection, CCL2 and IL-1b were upregulated only in μBS." (PMID 30619100, 2018). "The role of IL-1α in host resistance to infection and how TNF-α protects against infections have been recently updated." (PMID 30619296, 2018). "O. tsutsugamushi lacks LPS, but induces TNFα expression during infection of human patients, experimentally infected mice, primary cells, and cultivated host cells." (PMID 29734393, 2018). "As with IL-1β, mRNA levels of the proinflammatory cytokine TNF were significantly upregulated compared to those of the uninfected controls throughout both infection time courses." (PMID 29263113, 2018). "This study therefore determined the levels of cytokines (IL-10, IFN-γ and TNF-α) that are linked with the ability of MTB to evade the host’s immune system and mediate long-term infections in the lungs, leading to chronic tuberculosis." (PMID 30583589, 2018). "These increases agree with previous studies where infections of human macrophages with both Mtb H37Rv and Mtb H37Ra led to TNF-α expression." (PMID 30204787, 2018). "We observed a trend towards increased levels of TNFα, IL-6, IL-1β, and IL-1α in the lung tissue of p110δE1020K-GL mice at 24 h post-infection." (PMID 30093657, 2018). "In our study, we only found significant difference of TNF-α response in the 2000 CFU level of infection between the two strains, same as other cytokines including IL-4, IL-10, GM-CSF, IL-1β, IL-2, IL-6, IL-13, and IL-18." (PMID 30577452, 2018). "In MLN, cytokine mRNA levels were mostly unaltered upon infection, with the exception of IL-10 and TNF-α; both cytokines showed significantly elevated expression levels in infected animals (W = 255, P = 0.046 and W = 257, P = 0.040, respectively)." (PMID 29973271, 2018). "In mesenteric lymph nodes (MLN), IL-10 and TNF-α levels were elevated while splenic cytokine expression was unaltered upon infection." (PMID 29973271, 2018). "INH+NAC treatment also resulted in a significant decrease in the levels of TNF-α at both 8 days and 15 days (three-fold decrease) post-infection compared to untreated control category." (PMID 30258443, 2018). "This is further supported by the randomized control trials in which similar infection rates were reported between placebo and TNF inhibitor arms." (PMID 30555464, 2018).